CCEPR (cervical carcinoma expressed PCNA regulatory lncRNA )
Synonyms: CCHE1; lncRNA-CCHE1
Gene: Long non-coding RNA gene on chromosome 10 (59,173,365 to 59,176,453, reverse strand). Ensembl gene ENSG00000308499.
Diseases named in the same sentence as CCEPR in open-access papers:
CCEPR is named in the same sentence as 14 diseases in open-access papers, as found by Europe PMC text mining. Sharing a sentence is not in itself a finding about the gene and the disease. The quoted sentences say what the papers report.
cervical carcinoma (16 papers, 2017 to 2025). A carcinoma arising from either the exocervical squamous epithelium or the endocervical glandular epithelium. "For this reason, CCEPR is also known as cervical carcinoma high-expressed long non-coding RNA 1 (CCHE1)." (PMID 35774512, 2022). "Consistent with previous findings, we found that CCEPR overexpression contributes to proliferation of cervical cancer cell lines." (PMID 32326624, 2020). "LncRNA CCHE1 (cervical carcinoma expressed PCNA regulatory lncRNA) promoted carcinogenesis and indicated a poor prognosis of hepatocellular carcinoma via activation of ERK/MAPK pathway." (PMID 32509569, 2020). "CCEPR (cervical carcinoma expressed PCNA regulatory lncRNA, GenBank number AK055418) is a novel identified lncRNA with 2504 nucleotides in length and localized at the chromosome 10." (PMID 28574830, 2017). "Expression of the cervical carcinoma expressed PCNA regulatory (CCEPR) lncRNA (also referred to as cervical carcinoma high-expressed long non-coding RNA 1; CCHE1) is highly upregulated in cervical cancers and expression correlates with tumor size and poor prognosis of cervical cancer patients." (PMID 32326624, 2020). "Recently, CCEPR originally was identified as a powerful tumor biomarker for cervical cancer." (PMID 28574830, 2017). "CCEPR was previously reported to interact with PCNA and regulate cervical carcinoma occurrence and progression." (PMID 28574830, 2017). "CCEPR (cervical carcinoma expressed PCNA regulatory lncRNA) is a novel identified lncRNA that acts as a potential biomarker and involves in development and progression of cervical carcinoma." (PMID 28574830, 2017).
bladder cancer (1 paper, 2017). "In conclusions, these findings demonstrated that CCEPR plays an important regulatory role in bladder cancer and may serve as a potential diagnostic biomarker and therapeutic target." (PMID 28574830, 2017). "In conclusion, these findings demonstrated that CCEPR plays an important regulatory role in bladder cancer and may provide a promising diagnostic and therapeutic target in bladder cancer." (PMID 28574830, 2017). "Our results suggested that CCEPR plays an key role and may serve as a promising diagnostic and therapeutic target for bladder cancer." (PMID 28574830, 2017). "In this study, we found that the expression of CCEPR is significantly increased in bladder cancer tissues and cell lines, moreover, CCEPR promotes proliferation and suppresses apoptosis of bladder cancer cells in vitro." (PMID 28574830, 2017). "In this study, we found that CCEPR was significantly up-regulated in bladder cancer." (PMID 28574830, 2017). "The expression of CCEPR in bladder cancer tissues and cell lines was detected by qRT-PCR." (PMID 28574830, 2017). "In this study, we found the expression level of CCEPR is significantly increased in bladder cancer and CCEPR could promote proliferation and suppresse apoptosis in bladder cancer cells." (PMID 28574830, 2017). "CCEPR mRNA levels was up-regulated in bladder cancer cell lines." (PMID 28574830, 2017). "We further evaluated whether CCEPR regulates the migration and invasion of bladder cancer cells." (PMID 28574830, 2017). "We found CCEPR upregulates the expression of PCNA and serves as a key regulator in bladder cancer development and progression." (PMID 28574830, 2017). "CCEPR mRNA levels were signifcantly up-regulated in bladder cancer tissues compared to corresponding non-tumor tissues." (PMID 28574830, 2017). "The results indicated that CCEPR does not regulate cell migration and invasion in bladder cancer." (PMID 28574830, 2017).
tumor (7 papers, 2017 to 2025). "High level CCEPR expression has also been noted in other tumor types including osteosarcoma, uroepithelial bladder carcinoma, non-small cell lung carcinoma, hepatocellular carcinoma and colorectal carcinoma." (PMID 32326624, 2020).
cancer (4 papers, 2017 to 2023). A tumor composed of atypical neoplastic, often pleomorphic cells that invade other tissues. "Mechanistically, we found CCEPR upregulates the expression of PCNA in mRNA and protein level to promote cancer growth." (PMID 28574830, 2017).
CCEPR also shares sentences with these, for which no sentence is quoted: hepatocellular carcinoma (3 papers); breast carcinoma (2); melanoma (2); non-small cell lung carcinoma (2); osteosarcoma (2); coronary artery disease (1); gastric cancer (1); lymph node metastasis (1); oral squamous cell carcinoma (1); urothelial bladder carcinoma (1).